DYRK4 (dual specificity tyrosine phosphorylation regulated kinase 4)
Description:
Possible non-essential role in spermiogenesis.
Tractability: Small molecule: a high-quality ligand is known; it belongs to a druggable protein family. PROTAC: ubiquitination databases record sites on it; a small molecule that binds it is known.
Target class: Kinase; CMGC protein kinase group; CMGC protein kinase DYRK family; Protein Kinase; Enzyme
Gene: Protein-coding gene on chromosome 12 (4,562,208 to 4,615,302, forward strand). Ensembl gene ENSG00000010219.
Subcellular location: Cytoplasm (Isoform 1); Cytoplasm (Isoform 4); Nucleus
Subcellular location (Human Protein Atlas): Vesicles
Gene Ontology:
Molecular function: protein binding; ATP binding; protein kinase activity; protein serine kinase activity; protein serine/threonine/tyrosine kinase activity; protein tyrosine kinase activity
Cellular component: cytoplasm; nucleus; cytoskeleton
Genetic constraint (gnomAD): Loss-of-function variants: 63 observed, 69.49 expected, observed/expected ratio (o/e) 0.91, 90% interval 0.74 to 1.12. The upper end of that interval is the gene's LOEUF score, 1.12, which puts it in group 4 of 6, group 1 being the genes least tolerant of losing a copy. Missense variants: 729 observed, 791.76 expected, observed/expected ratio (o/e) 0.92, 90% interval 0.87 to 0.98. Synonymous variants: 271 observed, 299.82 expected, observed/expected ratio (o/e) 0.9, 90% interval 0.82 to 1.
Homologues: Orthologues: chimpanzee DYRK4 (98% identical), macaque DYRK4 (94% identical), dog DYRK4 (80% identical), pig DYRK4 (80% identical), rabbit DYRK4 (79% identical), rat Dyrk4 (75% identical), mouse Dyrk4 (73% identical), guinea pig DYRK4 (60% identical), zebrafish dyrk4 (48% identical), Drosophila melanogaster Dyrk2 (41% identical), Caenorhabditis elegans C16A11.10 (13% identical), Caenorhabditis elegans Y111B2A.1 (12% identical). Paralogues in human: DYRK2 (38% identical), DYRK3 (37% identical), DYRK1A (24% identical), HIPK2 (24% identical), HIPK3 (24% identical), DYRK1B (23% identical), HIPK1 (23% identical), CLK3 (20% identical), CLK1 (20% identical), CLK4 (19% identical), HIPK4 (18% identical), CLK2 (18% identical).
Diseases named in the same sentence as DYRK4 in open-access papers:
DYRK4 is named in the same sentence as 5 diseases in open-access papers, as found by Europe PMC text mining. Sharing a sentence is not in itself a finding about the gene and the disease. The quoted sentences say what the papers report.
lung carcinoma (1 paper, 2025). "A tumorigenic chimeric transcript, RAD51AP1-DYRK4, enhances the activation of MEK/ERK signaling and increases the invasiveness of ductal mammary carcinomas and hypomethylation of DYRK4 in peripheral blood is associated with increased lung cancer risk." (PMID 39702801, 2025).
viral infection (1 paper, 2025). "Moreover, Dyrk4-knockout mice are more susceptible to viral infection." (PMID 39702801, 2025). "To assess the importance of Dyrk4 in host defense against viral infection in vivo, we infected 8-week-old Dyrk4+/+ and Dyrk4−/− mice with VSV via tail vein injections and monitored their survival rates." (PMID 39702801, 2025). "To probe the mechanism of DYRK4 in the innate antiviral response, we first investigated the cellular localization of DYRK4 before and after viral infection." (PMID 39702801, 2025). "Endogenous coimmunoprecipitation experiments revealed that DYRK4 was constitutively associated with IRF3 in uninfected cells and that the interaction between DYRK4 and IRF3 increased to high levels at 8 and 12 h of viral infection." (PMID 39702801, 2025). "The underlying mechanism involves DYRK4 acting as a scaffold protein to recruit TRIM71 and LUBAC to IRF3, increasing IRF3 linear ubiquitination, maintaining IRF3 stability and activation during viral infection, and promoting the IRF3-mediated antiviral response." (PMID 39702801, 2025). "DYRK4 acts as a scaffold protein to recruit TRIM71 to interact with IRF3, increasing IRF3 linear ubiquitination, maintaining IRF3 stability during viral infection, and promoting IRF3-mediated antiviral responses." (PMID 39702801, 2025). "The results revealed that overexpression of DYRK4 stabilized the exogenous or endogenous IRF3 protein, and under conditions of viral infection, overexpression of DYRK4 extended the half-life of the exogenous IRF3 protein but did not affect IRF3 transcription." (PMID 39702801, 2025). "Since the interaction between DYRK4 and IRF3 depends on viral infection, DYRK4 affects IRF3 ubiquitination during viral infection." (PMID 39702801, 2025). "DYRK4 acts as a scaffold protein to recruit TRIM71 and LUBAC to IRF3, thereby increasing its linear ubiquitination, maintaining IRF3 stability and activation during viral infection, and promoting the IRF3-mediated antiviral response." (PMID 39702801, 2025). "This study establishes important roles for DYRK4 in virus-triggered IRF3 activation, IFNβ induction, and the cellular antiviral response and provides a mechanistic explanation of how IRF3 remains stable before and after viral infection." (PMID 39702801, 2025).
cancer (5 papers, 2020 to 2025). A tumor composed of atypical neoplastic, often pleomorphic cells that invade other tissues. "Eight understudied kinases were found to have hotspot mutations in at least one cancer (CDC42BPA, DYRK1B, DYRK4, LMTK3, MAPK15, NEK7, TSSK1B, and TTBK1), with DYRK4, LMTK3, MAPK15, and NEK7 all having significant hotspot mutations in STAD." (PMID 33205077, 2020). "Although in most cancers, DYRK4 contributes to cell cycle activation, its expression was not predicted in association with cancer pathways in COAD." (PMID 35454940, 2022). "The results showed a trend of a higher expression level in cancer tissues for ISG15, CAPN7, SEMA3A, and DYRK4 genes." (PMID 35008303, 2021).
tumor (2 papers, 2018 to 2022). "In correlation with DYRK3 and DYRK4 overexpression in tumors vs. normal, promotor methylation was significantly decreased in different tumor stages compared to normal." (PMID 35454940, 2022). "Investigating the mRNA expression in normal vs. tumor samples, DYRK3 and DYRK4 were found to have significantly lower methylation level compared to the control in COAD." (PMID 35454940, 2022). "In contrast, DYRK1B and DYRK4 tumor expression was not correlated to MYCN amplification status, and DYRK1A was actually lower in tumors with MYCN amplification." (PMID 29977157, 2018). "Both DYRK1A and DYRK2 showed a significantly lower expression in READ tumor vs. normal tissues, whereas DYRK1B, DYRK3 and DYRK4 had no significant change in expression." (PMID 35454940, 2022).
infection (1 paper, 2025). The state of being infected such as from the introduction of a foreign agent such as serum, vaccine, antigenic substance or organism. "Following four days of infection, serum analysis demonstrated that overexpressing DYRK4 reduced HBsAg and HBeAg levels." (PMID 40303300, 2025).